IL1B (interleukin 1 beta)
Diseases named in the same sentence as IL1B in open-access papers (continued):
Sharing a sentence is not in itself a finding about the gene and the disease.
type 2 diabetes (continued). "The involvement and therapeutic potential of IL-1β in the treatment of type 2 diabetes was recently demonstrated by treatment with the IL-1β receptor antagonist Anakinra, which resulted in improved beta cell secretory function and glycaemia control in human type 2 diabetic patients." (PMID 20948968, 2010). "Interestingly, similar localization within/around islets was also described in NOD mouse and type 2 diabetic humans, and it is known that pro-inflammatory cytokine activities, like those of IL-1β and TNF-α, involve ROS generation." (PMID 19654863, 2009). "We have demonstrated that resistin mRNAexpression from human peripheral monocyte-enriched mononuclear cells iselevated in type 2 diabetic women, compared to healthy control women, inparallel with significant increases in mononuclear IL-1β, TNF-α, and IL-6 mRNAexpression." (PMID 19125180, 2008). "In patients with type 2 diabetes and a high cardiovascular risk, 30 days of therapy with empagliflozin reduced IL-1β and TNF-α production by human macrophages generated from PBMC ex vivo in presence of M-CSF; serum levels of IL-18 and IL-1β were decreased as well." (PMID 40004134, 2025). "Moreover, as IL-1β serves as a universal pro-inflammatory cytokine, this vaccine could also have an effect on other IL-1β-driven diseases, as indicated by previous preclinical and clinical vaccination studies within RA and Type 2 Diabetes." (PMID 35632584, 2022). "To investigate the role of mtDNA in chronic inflammation in type 2 diabetes, we analyzed whether the elevated mtDNA levels could affect the IL-1β levels, which is a critical pro-inflammatory cytokine regulated by inflammasomes during chronic inflammation, in patients with type 2 diabetes." (PMID 30965677, 2019). "Thus, IL-1β contributes to the progression of chronic kidney disease in type 2 diabetes and might therefore be a valuable therapeutic target, potentially in combination with drugs with different mechanisms-of-action such as RAS and SGLT2 inhibitors." (PMID 31191559, 2019). "Notably, the ccf-DNA (ccf-DNA #1 and ccf-DNA #2) from two independent patients with type 2 diabetes resulted in a higher expression of cleaved caspase-1 and cleaved IL-1β in response to poly(dA:dT) stimulation compared with the vehicle control (control), although pro-IL-1β expression was unchanged." (PMID 30965677, 2019). "Among subjects at higher risk of type 2 diabetes, an acute postprandial intervention of MUFA breakfast (72 E%) containing macadamia nut oil showed that several inflammatory genes were upregulated in subcutaneous adipose tissue (MCP-1, IL-1β, IL-6, IL-6R, TNF-α and TNFRSF1A)." (PMID 28076613, 2017). "Overall, although whether glucose regulates the expression of IL-1β or IL-1ra in human islets remains controversial, it has been well established that local and/or systemic IL-1β's play an important role in the progression of islet dysfunction and β cell apoptosis in type 2 diabetes." (PMID 21113299, 2010). "Wang’s animal study stands alone in demonstrating the increased expression of pro-inflammatory cytokines TNF-α, IL-6 and IL-1β and the decreased expression of anti-inflammatory cytokines IL-4 and IL-10 in the midbrain of MPTP-treated type 2 diabetic mice." (PMID 40672460, 2025). "Additionally, to evaluate the effects of type 2 diabetes on neuroinflammation, Müller cell and microglia reactivity was also assessed by immunofluorescence in retinal cryosections, along with the assessment of IL-1β and TNF protein levels in retinal homogenates by Western blot and ELISA." (PMID 40898311, 2025). "Secondly, the comprehensive analysis of a broad range of biomarkers, including D-dimer and IL-1β, allows for a detailed evaluation of the mechanisms behind ART-related side effects, particularly in patients with comorbid conditions like type II diabetes." (PMID 39860995, 2025).
type 2 diabetes (continued). "Studies have shown that diabetic patients with type 2 diabetes have high levels of NLRP3 in monocytes, increased inflammasome activity, and elevated levels of IL-1β and IL-18 in peripheral blood." (PMID 40362167, 2025). "However, type 2 diabetes mellitus (T2DM) patients display macrophage infiltration of the endocrine pancreas and chronic elevation of IL-1β contributes to β-cells damage." (PMID 40874857, 2025). "Previous studies have reported that cold exposure increases systemic inflammatory cytokines such as IL-1β, IL-6, and TNF-α in patients with type 2 diabetes." (PMID 40270542, 2025). "In patients with type 2 diabetes, SGLT2 inhibitors decrease the levels of proinflammatory cytokines (TNF-α, IL-6, and IL-1β) and attenuate the activity of NLRP3 inflammasome." (PMID 40004134, 2025). "In our analysis, the apoptotic osteocytes were raised in number and the expression levels of TNF-α and IL-1β were increased in the T2DM rats, which likely contributes to the increased bone resorption observed in type 2 diabetes." (PMID 40943086, 2025). "In islets isolated from patients with type II diabetes and mice islets or INS1 cells treated with IL-1β and TNF-α, SIRT3 expression is markedly downregulated, which impairs β-cell function via abnormal elevation of ROS levels and amplification IL-1β synthesis." (PMID 39372420, 2024). "Peripheral blood-derived macrophages from drug-naïve patients with type 2 diabetes show increased expression of NLRP3 and ASC along with caspase-1 activation and IL-1β maturation." (PMID 38681198, 2024). "Hesperidin also alleviated neuroinflammation through the reduction of IL1-β and TNF-α in patients with type 2 diabetes." (PMID 38794179, 2024). "Correlating these data, we can assume that CCL2, CCL5, IL-6, IL-1β, and leptin can play a significant role in MDSC recruitment in the adipose tissue of patients with type 2 diabetes." (PMID 39518420, 2024). "Systemic levels of TNF-a, IL-1b, IL-6, and CRP are elevated in both type 1 and type 2 diabetes patients, which is a result of the chronic activation of pro-inflammatory pathways within insulin-target cells." (PMID 38904046, 2024). "Obese and Type 2 Diabetes patients were reported to have elevated expression of all classical inflammasome components, including NLRP3, ASC, Caspase-1 and IL-1β in both liver and visceral adipose tissue." (PMID 36175539, 2023). "Clinical data also show that systemic levels of pro-inflammatory cytokines, including tumor necrosis factor (TNF)-a, interleukin (IL)-1b, IL-6, and CRP are elevated in patients with both type 1 and type 2 diabetes." (PMID 36769405, 2023). "For example, ω-3 fatty acids can alleviate high-fat food-induced type 2 diabetes by inhibiting NLRP3 inflammatory vesicles and reducing the secretion of IL-1b, a key factor in inflammation." (PMID 37047050, 2023). "The vaccination of mice with IL-1β displayed on keyhole limpet hemocyanin (KLH) or VLPs has been shown to induce therapeutic antibodies for the treatment of RA and type 2 diabetes, respectively." (PMID 35632584, 2022). "Glyburide, an ATP-sensitive K+ channel inhibitor used in the treatment of type 2 diabetes, is capable of inhibiting the NLRP3 inflammasome and decreasing IL-1β production." (PMID 35456141, 2022).
type 2 diabetes (continued). "The present results revealed that B. vernae extract could significantly reduce the TNF-α, IL-1β, and IL-6 levels of diabetic rats, suggesting that B. vernae might have potential anti-inflammation activity, which is beneficial to improve the inflammatory state of type 2 diabetes." (PMID 32636751, 2020). "In a type 2 diabetes (T2D) model, MPTP treatment upregulates the level of oligomeric α-syn in both pancreas and midbrain, resulting in increased IL-1β secretion via NLRP3 activation, and ultimately exacerbates the loss of DA neurons." (PMID 33212758, 2020). "In type-2 diabetic patients, TNF-α was significantly decreased after the treatment with Brazilian green propolis, however IL-1β and IL-6 were significantly increased." (PMID 31717277, 2019). "The mtDNA from patients with type 2 diabetes induced AIM2 inflammasome-dependent caspase-1 activation, and IL-1β and IL-18 secretion in macrophages." (PMID 30965677, 2019). "Glyburide, a drug commonly used in type 2 diabetes, can also prevent NLRP3-dependent IL-1β production." (PMID 28192528, 2017). "In a series of experiments using in vitro models, intrarenal inflammasome activation elevated intrarenal IL-1β and NLRP3 mRNA levels were increased in both db/db mice (modelling type 2 diabetes) and murine streptozotocin-induced type 1 diabetic mice." (PMID 28708885, 2017). "This is in agreement with previous results determining IL-1β in this model, although increased serum levels of TNF-α have been detected in high fat fed/streptozotocin-induced type 2 diabetic rats." (PMID 25518980, 2014). "In this paper, recent findings regarding the effects of cytokines including IL-1β, IFN-γ, TNF-α, leptin, resistin, adiponectin, visfatin, and PANDER on pancreatic β-cell dysfunction and type 2 diabetes will be summarized and discussed." (PMID 21113299, 2010). "In the present study, we have demonstratedthat in type 2 diabetes, there is an increased mRNA expression of resistin,along with significant increases in TNF-α, IL-6, and Il-1β mRNA expression bythe peripheral circulating mononuclear cells." (PMID 19125180, 2008). "Decreases serum levels of IL-1β and TNF-α in patients with type II diabetes mellitus." (PMID 41141350, 2025). "Peripheral levels of Interleukin-1β (IL-1β), Interleukin-6 (IL-6), and tumor necrosis factor-α (TNF-α) are elevated during first-episode psychosis and psychotic relapses in schizophrenia, as well as in the pathogenesis and complications of type 2 diabetes." (PMID 40426670, 2025). "Participants with type 2 diabetes who consumed oleocanthal-enriched HP-EVOO experienced enhanced antiplatelet effects, lower inflammatory cytokine levels (TNF-α, IL-1β, and IL-6, p < 0.05) and enhanced anti-inflammatory IL-10 concentration (p = 0.032) compared to butter, olive oil and EVOO groups." (PMID 40136590, 2025). "We found that at the end of treatment, XOMA052 was able to alleviate chronic inflammation in type 2 diabetes by down-regulating the production of IFN-γ and IL-17a in peripheral blood, reducing inflammatory cytokines TNF-α, IL-1β, and IL-6, and reducing β cell apoptosis and promoting proliferation." (PMID 40066372, 2025). "In patients with type 2 diabetes, GLP-1RAs lowered the plasma levels of IL-18 and IL-1β." (PMID 41424495, 2024). "In addition to Aβ accumulation, previous studies illustrated an increase in levels of proinflammatory cytokines such as IL-1β, IL-6, and TNF-α in patients with type 2 diabetes." (PMID 38510866, 2024). "This is in accordance with previously published report highlighting those patients with type 2 diabetes treated with IL-1β-inhibitors exhibit reductions in hs-CRP and IL-6 without changes in HbA1c." (PMID 38725572, 2024). "(2018) reported that dietary supplementation of L-carnosine (500 mg/kg) resulted in decreased fasting glucose and HbA1c levels, as well as increased serum TG and HDL levels in patients with type 2 diabetes, without affecting IL-6 and IL-1β levels." (PMID 38198911, 2023).
type 2 diabetes (continued). "Similarly, the expression of the proinflammatory cytokine IL1B mRNA and CXCL8 showed a clear trend of increase with a high correlation to HIF1A mRNA levels in samples from type 2 diabetic patients living at high altitude." (PMID 34651203, 2022). "We measured the IL-1β levels in plasma from 141 patients with type 2 diabetes and 22 healthy subjects without type 2 diabetes as controls." (PMID 30965677, 2019). "In addition, miR-296-3p can reduce the resistance of αTC1–6 cells to apoptosis induced by cytokines, such as IFN-γ, IL-1β and TNF-α, suggesting its involvement in the regulation of Type 2 diabetes." (PMID 30134788, 2018). "During the development of type 2 diabetes, there is an increased secretion of TNF-α from infiltrated macrophages in the adipose tissues, which induces the production of several inflammatory cytokines, including IL-1β." (PMID 28405188, 2017). "Furthermore, various longitudinal studies have shown that elevated levels of CRP, IL-1β, IL-6, and TNF-α predict the development of type 2 diabetes." (PMID 27034691, 2016). "One research of type 2 diabetes has shown that the maturation of caspase-1 and IL-1β, the sign of NLRP3 inflammation activation, did not required TXNIP in bone marrow-derived macrophages." (PMID 25136835, 2014). "Masters and colleagues demonstrated that soluble oligomers of islet amyloid polypeptide (IAPP), a protein that forms amyloid deposits in the pancreas during type 2 diabetes, could be endocytosed and trigger the NLRP3 inflammasome and generate mature IL-1β." (PMID 23762269, 2013). "Additionally, type 2 diabetic patients showed elevated levels of NLRP3, ASC, IL-1β, and IL-18 mRNA and protein expression in monocyte-derived macrophages, compared with those in healthy control subjects." (PMID 23843683, 2013). "All of the pro-inflammatory cytokines evaluated (IL-1β, IL-6, IL-8, IL-10, IL-12p70, and TNF-α) were increased in patients with type 2 diabetes, although only the increases in TNF-α, IL-8, and IL-12 p70 were statistically significant in comparison to healthy individuals (P < 0.05)." (PMID 22500980, 2012). "In addition, IL-1β, IFN-γ, and D-dimer emerged as independent predictors of gastrointestinal complications, reinforcing the critical role of systemic inflammation in developing these adverse effects, particularly in patients with HIV and type II diabetes." (PMID 39860995, 2025). "Analysis of macrophages from people with type 2 diabetes treated with empagliflozin or sulfonylurea demonstrated that the SGLT2 inhibitor was more efficient in the attenuation of NLRP3 activation in macrophages as compared to sulfonylurea, and more efficiently suppressed IL-1β secretion." (PMID 40004134, 2025). "Similarly, islets isolated from healthy donors but not from individuals with type 2 diabetes secrete insulin in response to IL-1β." (PMID 39496966, 2025). "Among them, HIF1A may indirectly activate NLRP3, which encodes for NLRP3 inflammasomes, contributing to the inflammatory responses via IL-1β activation, which is down-regulated to a greater extent in BPD-DS in this study, and could be of key importance in the development of type 2 diabetes." (PMID 35739539, 2022). "Ventricular myocytes isolated from control rats were incubated 24 h in DMEM supplemented with either plasma obtained from non-diabetic animals; or plasma extracted from type 2 diabetic animals, with or without added TNFα (50 μM) and IL-1b (50 μg/mL) receptor blockers." (PMID 34202017, 2021). "Additionally, our results revealed that B. vernae extract or metformin treatment for 30 days significantly decreased (P < 0.01) serum FBG, INS, HOMA-IR, GSP, TNF-α, IL-1β, and IL-6 levels, whereas increased serum ISI levels (P < 0.01) in type 2 diabetic rats, compared with the model group." (PMID 32636751, 2020).
type 2 diabetes (continued). "As a whole, our results suggest that the effect of cytokines (IL-1β, IL-6 and TNF-α) on the incidence of type 2 diabetes might be mediated by other factors; they also suggest that these markers do not improve risk prediction as assessed by a validated type 2 diabetes risk score." (PMID 23251619, 2012). "Although, IL-1β does not appear to have a pivotal role in controlling inflammation in RA, it contributes to synovial joint damage and may have a role in comorbidities such as type 2 diabetes and cardiovascular disease." (PMID 33605409, 2021). "Interestingly, we have previously demonstrated that monocyte-enriched mononuclear cells from individuals with type 2 diabetes show increased levels of visfatin, resistin, TNF-α, IL-6, and IL-1β mRNA expression indicating that hyperinsulinemia and hyperglycemia could enhance cytokine production." (PMID 23484124, 2013). "IL-1β is a critical effector molecule in non-obese diabetic (NOD) mice models of T1D, and it’s also an important inflammatory mediator of type II diabetes." (PMID 36186138, 2022). "The mtDNA, from patients with type 2 diabetes, induced absent in melanoma 2 (AIM2) inflammasome-dependent caspase-1 activation and IL-1β and IL-18 secretion in macrophages." (PMID 30965677, 2019). "Serum samples from several cohorts with type 2 diabetes were analyzed for the presence of anti-LCSFA IgG, the cytokine IL-1β, and nonesterified fatty acids." (PMID 26633920, 2015).